KMT2A (lysine methyltransferase 2A)
Diseases named in the same sentence as KMT2A in open-access papers (continued):
Sharing a sentence is not in itself a finding about the gene and the disease.
acute monocytic leukemia (7 papers, 2005 to 2025). Acute monoblastic leukemia (AML-M5), is one of the most common subtypes of acute myeloid leukemia (AML) that is either comprised of more than 80% of monoblasts (AML-M5a) or 30-80% monoblasts with (pro)monocytic differentiation (AML-M5b). "P1 was also significantly enriched in WHO subtype AML with KMT2A rearrangement (q < 0.05), acute monocytic leukemia, and AML with CBFB::MYH11 fusion." (PMID 38724673, 2024). "KMT2A-rearranged acute monoblastic leukemia is usually negative for CD34; however, this neoplasm case falls within the uncommon 5% of cases that demonstrate CD34 positivity." (PMID 40149468, 2025).
Anxiety (6 papers, 2021 to 2025). Intense feelings of nervousness, tension, or panic often arise in response to interpersonal stresses. "The loss of Kmt2a in forebrain neurons results in behavioral changes, such as increased anxiety, social behavior deficit, and impaired working memory, in an animal model." (PMID 34947998, 2021). "Post-natal and adult mice with KMT2A deficiency lead to changes in gene expression patterns as it relates to neuronal plasticity, with impaired cognition and increased anxiety, supporting a causal role for KMT2A loss of function in a spectrum of neurodevelopmental syndromes." (PMID 39303915, 2024). "Additionally, neuronal deletion of KMT2A in the prefrontal cortex, ventral striatum, and nucleus accumbens has been associated with working memory deficits and increased anxiety in mouse models, implicating that normal neurogenesis may rely on the downregulation of KMT2A." (PMID 36062544, 2023). "Selective ablation of lysine (K) methyltransferase 2a (Kmt2a), a HMT specific for H3K4, which is linked to active transcription, but not the ortholog Kmt2b, in adult ventral striatum/nucleus accumbens neurons, however, markedly increased anxiety-like behavior in multiple behavioral paradigms." (PMID 36946487, 2024).
ovarian carcinoma (6 papers, 2012 to 2024). A malignant neoplasm originating from the surface ovarian epithelium. "Recurrently mutated ovarian cancer driver genes, including LRP1B, KMT2A, ARID1A, KMT2C and ATRX were also found in two cell lines." (PMID 37525498, 2023).
sarcoma (6 papers, 2020 to 2024). A usually aggressive malignant neoplasm of the soft tissue or bone. "In addition, we systematically searched for KMT2A structural variants in a comprehensive genomic profiling database of 14,680 sarcomas interrogated by targeted next-generation DNA and/or RNA sequencing." (PMID 32461620, 2020). "Nonetheless, clinicopathologic and molecular descriptions of KMT2A-rearranged sarcomas remain limited." (PMID 32461620, 2020). "In summary, KMT2A-fusion-positive sarcomas most commonly exhibit sclerosing epithelioid fibrosarcoma-like morphology and complex YAP1–KMT2A–YAP1 fusions." (PMID 32461620, 2020). "The remaining 16 KMT2A-rearranged sarcomas in our cohort exhibited diverse histologic subtypes, each with unique novel fusion partners." (PMID 32461620, 2020). "YAP1 is a commonly recurrent partner to KMT2A, and YAP1–KMT2A fusion-positive sarcomas exhibit sclerosing epithelioid fibrosarcoma-like histomorphology." (PMID 32461620, 2020). "Fusions between YAP1 and KMT2A were detected by RNA-based assays in all 16 sarcomas, six of which were additionally confirmed by orthogonal DNA-based assays." (PMID 32461620, 2020). "To assess the overall frequency of KMT2A structural alterations in sarcomas, we queried a genomic profiling database of 14,680 sarcomas, in which there was coverage of KMT2A by DNA and/or RNA-based sequencing methods." (PMID 32461620, 2020). "In conclusion, in a comprehensive genomic profiling database of 14,680 sarcomas, KMT2A rearrangements were observed in 0.2% of cases." (PMID 32461620, 2020). "We characterized the clinicopathologic and molecular features of KMT2A fusion-positive sarcomas, including KMT2A breakpoints, rearrangement partners, and concurrent genetic alterations." (PMID 32461620, 2020). "Consistently, these sarcoma cells have upregulation of KMT2A canonical targets, that is, HOX genes." (PMID 39303915, 2024). "In comparison to hematologic malignancies in which the KMT2A N-terminus is preserved, sarcomas with YAP::KMT2A and VIM::KMT2A rearrangement have KMT2A as the 3′ fusion partner." (PMID 39303915, 2024). "As expected, lung tumors with driver fusions harbored mostly EML4/ALK fusions, sarcomas were driven mostly by EWSR1-related and PAX3/FOXO1 fusions, while hematologic malignancies with a spectrum of BCR/ABL1, KMT2A-related, and IGH/MYC fusions." (PMID 33889297, 2021). "Similarly, fusions involving driver genes largely or exclusively restricted to sarcoma (e.g. KMT2A::YAP1 in case 9) are readily detectable, as are the more sarcoma-specific copy number targets (e.g. COPS3 in case 17 and MYOCD in case 13)." (PMID 38997407, 2024). "Other unique and nonrecurrent KMT2A fusions occurred in sarcomas of diverse histologic subtypes with unclear significance." (PMID 32461620, 2020). "Second, given that the KMT2A CxxC-binding domain is integral to HOX gene regulation, it is notable that no increase in HOXA-related gene expression was detected by RNA sequencing in three YAP1–KMT2A fusion-positive sarcomas in a prior study." (PMID 32461620, 2020). "We also described the features of VIM–KMT2A sarcomas as well as sarcomas of diverse histologic subtypes that harbored unique nonrecurrent KMT2A fusions of unclear significance." (PMID 32461620, 2020).
B-cell lymphoma (5 papers, 2020 to 2024). "The FOXR1 gene and KMT2A in the 11q23 segment are related to the occurrence of B-cell lymphoma." (PMID 38172714, 2024). "Two large gene expression data sets were probed for the expression of IGF2BP3—the highest levels were seen among the B-cell lymphomas of a germinal center origin and well-established (KMT2A-rearranged and ETV6-RUNX1) and novel subtypes of B-ALL (e.g., NUTM1 and ETV6-RUNX1-like)." (PMID 33805930, 2021).
Down syndrome (5 papers, 2017 to 2025). "Misclassification incidents involving FUS::ERG fusions, KMT2A rearrangements in older adults, and Down Syndrome-associated AML highlight critical gaps in training data availability." (PMID 40730747, 2025).
gastric cancer (5 papers, 2022 to 2025). A primary or metastatic malignant neoplasm involving the stomach. "The result showed that KMT2A was an independent risk factor for the prognosis of gastric cancer patients." (PMID 38025523, 2023). "In this study, we demonstrated that KMT2A was highly expressed in gastric cancer and associated with poor outcomes of patients and revealed that KMT2A was significantly associated with stemness and increased nuclear β-catenin in gastric cancer." (PMID 38025523, 2023). "Meanwhile, a close association between KMT2A expression and β-catenin expression in gastric cancer was also observed; moreover, KMT2A regulated the translocation of β-catenin to the nucleus in gastric cancer cells." (PMID 38025523, 2023). "The findings will provide a solid foundation for the understanding of the association between KMT2A and stemness in gastric cancer." (PMID 38025523, 2023). "The result showed a close association between KMT2A expression and β-catenin expression in gastric cancer; moreover, the result from western blotting showed that also the high level of KMT2A protein was associated with high expression of β-catenin in clinical samples of gastric cancer." (PMID 38025523, 2023). "In the study, the prognostic value of KMT2A was demonstrated to be associated with poor outcome of gastric cancer patients and was recognized as a regulator of stemness in gastric cancer through regulating Wnt/β-catenin-induced expression of stemness-related genes." (PMID 38025523, 2023). "The results suggest that KMT2A could be used as a poor prognostic factor, and highly expressed KMT2A was significantly associated with shorter survival and risk of recurrence in gastric cancer patients." (PMID 38025523, 2023). "Furthermore, independent risk factors for the prognosis of gastric cancer patients with KMT2A high expression, compared to those with KMT2A low expression, were assessed using COX logistic regression analysis and log-rank test in 178 gastric cancer tissues." (PMID 38025523, 2023). "To address the issue on the molecular mechanism of KMT2A regulating β-catenin activation-induced stemness in gastric cancer, we identified the β-catenin-binding nuclear protein KLF11 by performing a Co-IP/MS analysis gastric cancer cells." (PMID 38025523, 2023). "Stem cell differentiation-related pathways, including stem cell differentiation and stem cell population maintenance, were significantly enriched in gastric cancer with high expression of KMT2A." (PMID 38025523, 2023). "To screen for stemness-related signaling pathways associated with KMT2A expression in gastric cancer, we performed gene set enrichment analysis (GSEA) by comparing the high and low KMT2A expression groups." (PMID 38025523, 2023). "To further unravel the mechanism of KMT2A in affecting the stemness in gastric cancer, we observed the change of stemness-related factors and cell proliferation in BGC-823 cells with KMT2A knockdown, compared to control cells." (PMID 38025523, 2023). "Altogether, the results suggested that KMT2A-induced stemness was dependent on the activation of Wnt/β-catenin signaling in gastric cancer cells." (PMID 38025523, 2023). "To define the association between KMT2A expression and stemness of gastric cancer, we performed GSEA of stemness-related signaling pathways and explored the correlation between KMT2A expression and a stemness-related marker set." (PMID 38025523, 2023). "The results of database analysis showed that the expression of KMT2A was significantly higher in gastric cancer tissues (n = 408) compared with that in normal gastric tissues (n = 211) (P < 0.01)." (PMID 38025523, 2023). "Together, KMT2A is an important epigenetic regulator of gastric cancer stemness, which provides a novel insight to the potential application of targeting against KMT2A in treating gastric cancer." (PMID 38025523, 2023). "The findings indicated the involvement of KMT2A in gastric cancer stemness by activating the WNT/β-catenin signaling." (PMID 38025523, 2023).
gastric cancer (continued). "Based on the findings, we further investigated the correlation between KMT2A expression and Wnt/β-catenin signaling in gastric cancer." (PMID 38025523, 2023). "In gastric cancer, KMT2A is recruited into the ANO1 promoter to induce H3K4 methylation of the ANO1 promoter to activate ANO1." (PMID 35058979, 2022). "To further explore the molecular mechanism of KMT2A regulating β-catenin activation-induced stemness in gastric cancer, we identified the β-catenin-binding nuclear proteins by performing a co-immunoprecipitation/mass spectrometry (Co-IP/MS) analysis in BGC-823 cells." (PMID 38025523, 2023). "Hence, it is necessary to further explore the mechanism by which KMT2A is involved in the stemness regulation of gastric cancer." (PMID 38025523, 2023). "In addition, to clarify the effect of KMT2A on the stemness of gastric cancer cells, we carried out a tumorsphere formation assay using BGC-823 cells." (PMID 38025523, 2023). "Moreover, to further investigate the relationship between KMT2A and stemness, we analyzed the correlation between KMT2A expression and the stemness-related marker set in gastric cancer using the GEPIA2 online web server." (PMID 38025523, 2023). "In addition, it was also demonstrated that KMT2A knockdown inhibited the translocation of β-catenin to the nucleus in gastric cancer BGC-823 cells." (PMID 38025523, 2023). "In conclusion, we demonstrated the effects of KMT2A on stemness of gastric cancer." (PMID 38025523, 2023). "Furthermore, we identified a critical role of KMT2A in promoting the stemness formation of gastric cancer cells using a tumorsphere formation assay." (PMID 38025523, 2023). "Recent studies have shown that KMT2A may play a recessive role in some solid tumors, such as gastric cancer." (PMID 35058979, 2022). "However, SOX2 suppression may be permissive for a sub-set of gastric cancers with CDX2 induction to acquire mutations in epigenetic modifier genes, including ARID1A, KMT2D, KMT2C, KMT2A, and KMT2B." (PMID 40149431, 2025). "Mechanistically, KMT2A activated β-catenin signaling, which served as a coactivator of KLF11, and promoted the expression of specific gastric cancer stemness-related molecules." (PMID 38025523, 2023). "The result showed that a significant correlation was found between KMT2A and the stemness-related gene sets, including tumor stemness-related signature (CD44/CD133/Sox2/OCT4) and gastric cancer-specific stemness signature (Sox/FOXM1)." (PMID 38025523, 2023). "Meanwhile, KMT2A did not only directly bind to β-catenin–KFL11 complex but also affect the methylation of KFL11 promoter, finally regulating the expression of FKL11 in gastric cancer cells." (PMID 38025523, 2023). "Mechanistically, KMT2A activated the translocation of β-catenin into the nucleus of gastric cancer cells, and then, β-catenin served as a coactivator of KLF11, which promoted the expression of specific gastric cancer stemness-related molecules, including SOX2 and FOXM1." (PMID 38025523, 2023). "However, the role of KMT2A in gastric cancer is not well established." (PMID 38025523, 2023).
intestinal cancer (5 papers, 2020 to 2023). "Recently, it is reported that KMT2A functions as an epigenetic regulator of cancer stemness in intestinal cancer." (PMID 38025523, 2023).
Myelodysplasia (5 papers, 2010 to 2025). Clonal hematopoietic stem cell disorders characterized by dysplasia (ineffective production) in one or more hematopoietic cell lineages, leading to anemia and cytopenia. "At diagnosis, our patient had a deletion of 11q23 involving monosomic KMT2A loss without rearrangement, which is considered an intermediate-risk feature, and U2AF1 mutation, which is considered an adverse-risk myelodysplasia-related gene mutation." (PMID 41008781, 2025).
renal fibrosis (5 papers, 2022 to 2025). A final common manifestation of a wide variety of chronic kidney diseases characterized by glomerulosclerosis and tubulointerstitial fibrosis. "Based on a previous study, MM‐102 and OICR‐9429, which are inhibitors of KMT2A, a methyltransferase of H3K4me3, inhibited renal fibrosis in mice with I/R injury." (PMID 37710084, 2023). "In a unilateral ureteral obstruction‐induced obstructive nephritis model, the KMT2A and H3K79me3‐binding protein menin complex up‐regulates the expression of α‐SMA and fibronectin in fibroblasts, thereby promoting renal fibrosis." (PMID 39888275, 2025).
thymoma (5 papers, 2020 to 2025). A neoplasm arising from the epithelial cells of the thymus. "Among other molecular alterations the thymic adenocarcinoma harbored a mutation in KMT2A c.2155A > C(p.S719R), while the type A thymoma harbored a different KMT2A mutation c.5343del(p.V178Yfs*38)." (PMID 38067300, 2023). "While CRCT1 was found to be fused with MAML2 in mucoepidermoid carcinomas, as in mucoepidermoid carcinomas elsewhere in the body, YAP1 was identified as the fusion partner of MAML2 in metaplastic thymomas and KMT2A in type B2 and B3 thymomas." (PMID 38067300, 2023). "In a subset of B2 and B3 thymomas the fusion partner is lysine methyltransferase 2A (KMT2A), resulting in KMT2A::MAML2 fusions." (PMID 38067300, 2023).
thyroid cancer (5 papers, 2019 to 2025). "Overexpression of KMT2A has been implicated in thyroid cancer, with its knockdown suppressing thyroid cancer cell proliferation." (PMID 40895628, 2025).
bladder cancer (4 papers, 2015 to 2024). "The most frequently mutated genes in ordinary bladder cancer are TP53x, KMT2A, SPTAN1, ERBB2, CREBBP, FAT1, ATM, and KMT2C." (PMID 36779496, 2023). "Additionally, the most frequently mutated genes in ordinary bladder cancer are KMT2C, ATM, FAT1, CREBBP, ERBB2, SPTAN1, and KMT2A." (PMID 39399176, 2024).